MDM2 (MDM2 proto-oncogene)
Diseases named in the same sentence as MDM2 in open-access papers (continued):
Sharing a sentence is not in itself a finding about the gene and the disease.
breast carcinoma (continued). "This oscillation is perturbed in MCF-7 breast cancer cells that carry the mdm2 SNP309 T to a G change (T→G) but is not perturbed in the breast cancer cell line ZR75-1 that does not have this change." (PMID 21223569, 2011). "Though MDM2 SNP309 has been implicated to affect survival in other tumors (for example,), as far as we know there are no other publications on breast cancer outcome and this polymorphism, except for a recent publication in BRCA1/2 carriers of Ashkenazi origin." (PMID 20021639, 2009). "MDM2 was rarely reported to be a prognostic factor in HCC, but was often reported in the maxillary sinus squamous cell carcinoma, in Egyptian esophageal carcinoma, in breast carcinoma, prostate adenocarcinoma, gastric cancer, and epithelial ovarian cancer." (PMID 20025780, 2009). "We conclude that MDM2 gene amplification occurs at a lower frequency in breast cancer than in non-epithelial tumours." (PMID 7734324, 1995). "In addition, molecular docking and simulation also identified IGF1R, MDM2, and SRC could be the prime diosgenin-modulated targets against breast cancer." (PMID 36686654, 2022). "Not many clinical trials have used MDM2 inhibitors in breast cancer patients." (PMID 34830174, 2021). "While this work was not performed in breast cancer cells, it is important to know that the induction of apoptosis is a mechanism by which this combination reduces tumor growth, since that is a pathway that is typically deregulated when MDM2 is overactive." (PMID 34830174, 2021). "Indeed, MDM2 is a negative prognostic marker and it has been shown that high MDM2 protein levels are detected in tumour biopsies from breast cancer patients with lymph node metastases." (PMID 32456234, 2020).
breast carcinoma (continued). "We correlated FKBP12 and MDM2 expression to patient clinicopathologic characteristics such as age at diagnosis, tumor size, histologic grade, lymph-node metastatic status, NPI, proliferation rate of breast cancer cells (Index of MIB-1), ER, PR, HER2, and molecular subtype." (PMID 31428819, 2019). "Furthermore, these data, collectively, could explain the different effect of MDM2 and MDMX SNPs in the distinct breast cancer subtypes." (PMID 30956778, 2019). "The PD0332991-induced downregulation of MDM2 and entry into senescence is observed in a number of different types of cancer cell lines, including those derived from well-differentiated and dedifferentiated liposarcoma (WD/DDLS), breast cancer, non-small cell lung cancer, and glioma." (PMID 29789718, 2018). "Therefore it is not surprising that MDM2 expression is a negative prognostic marker for breast cancer." (PMID 28615518, 2017). "In addition, protein complexes comprised of endogenously-expressed MDM2 and ERα proteins have not been characterized in breast cancer cells." (PMID 26909605, 2016). "Therefore, dually targeting MDM2 and NFAT1 could be a novel and effective approach to breast cancer therapy." (PMID 27105525, 2016). "Similarly Wasieleski and colleagues have not noted a higher frequency of MDM2 309 SNP G/G in younger BRCA1/2 breast cancer patients." (PMID 19226467, 2009). "Two very recent studies separately focusing on Indian women and Scottish Caucasian women also suggested no detectable association between MDM2 SNP309 and breast cancer, although this genetic polymorphism was associated with high grade nodal positive breast cancer in the latter population." (PMID 19144119, 2009). "This study therefore sought to sequence the MDM2 intron 1 region around SNP309 in detail and determine SNP frequencies from a control cohort of Scottish Caucasians (n = 275) and a cohort of geographically matched Scottish Caucasian women with breast cancer (n = 299)." (PMID 18828900, 2008). "In addition, knockdown of MDM2 results in a reduction of MMP2 gene expression and increase in MMP3, MMP10 and MMP13 gene expression and decreased growth and migration of breast cancer cells, and the mechanism may involve the interplay between MDM2 and prostate-specific membrane antigen (PSMA)." (PMID 33466790, 2021).
breast carcinoma (continued). "Moreover, this study used an experimental system quite different from our quantification of endogenous MDM2 mRNA in ≈100 human breast tumors, and included neither breast epithelial nor breast cancer cells, nor MDM2 promoter P2 with its potential modifying effects on MDM2 expression." (PMID 33202864, 2020). "Besides sarcoma, the protein profiles of cases with MDM2 amplification are discriminable from those with normal copy numbers for renal clear cell carcinoma, lung adenocarcinoma, thyroid carcinoma, breast cancer, ovarian carcinoma, and low-grade glioma (all currently not reported by OncoKB)." (PMID 30442178, 2018). "Therefore, current data suggest that homozygous GG but not TG genotype of MDM2 SNP309 may also accelerate the incidence of breast cancer among the female Taiwanese population." (PMID 19144119, 2009). "Secondly, given that MDM2 SNP309 may influence tumor development in the selected patient subgroup, the regional epidemiological study was highly relevant and should provide important information from which to better understand the role of MDM2 SNP309 on breast cancer formation." (PMID 19144119, 2009). "Therefore, it cannot be ruled out that MDM2 SNP309 may combine with these genetic factors to affect the development of breast cancer in Taiwanese women." (PMID 19144119, 2009). "In some cancers, such as retinoblastomas, breast carcinomas, and melanomas, the inhibition of MDM2 may not be sufficient to stop tumor progression because the cancers highly express MDMX, which is a structural homolog of MDM2." (PMID 36678521, 2022).
liposarcoma (368 papers, 2000 to 2026). A usually painless malignant tumor that arises from adipose tissue. "The diagnostic imperative is excluding well-differentiated liposarcoma via MDM2 fluorescence in situ hybridization (FISH), which has traditionally required surgical resection for adequate tissue sampling." (PMID 42253355, 2026). "Subtype-specific alterations were observed, including EWSR1 fusions in Ewing sarcoma and CDK4 and MDM2 amplifications in liposarcoma, reflecting well-established pathogenic mechanisms." (PMID 41562936, 2026). "This genomic hallmark has established liposarcoma as the lead clinical setting for MDM2-directed therapy." (PMID 41170373, 2025). "Positive MDM2 expression is often seen in well-differentiated liposarcomas and DDLPS, making it a key diagnostic marker." (PMID 39591300, 2024). "In conclusion, retropharyngeal liposarcomas pose diagnostic challenges, warranting reliance on MDM2 FISH analysis for accurate confirmation." (PMID 38586633, 2024). "Following the associations made, MDM2 immunopositivity in the case of liposarcoma is over 25% of the nuclei, while in the case of ALT/WDLS, it is over 50% of the nuclei (p < 0.001)." (PMID 38132190, 2023). "The presence of MDM2 and p16, both recognized liposarcoma markers, adds to their diagnostic usefulness." (PMID 38156143, 2023). "The MDM2 amplification represents the hallmark of well-differentiated liposarcoma/atypical lipomatous tumor, dedifferentiated liposarcoma, intimal sarcoma, as well as low-grade osteosarcoma." (PMID 37297833, 2023). "This amplification has been associated with heightened MDM2 protein expression and is linked to the process of de-differentiation in liposarcomas." (PMID 37627196, 2023). "In some retrospective studies, the degree of MDM2 amplification in de-differentiated liposarcoma was found to be associated with poor overall survival (OS) and reduced interval from the time of resection to the time of recurrence." (PMID 37298520, 2023). "MDM2 amplification represents the leading oncogenic pathway and diagnostic hallmark of liposarcoma, whose assessment is based on Fluorescence In Situ Hybridization (FISH) analysis." (PMID 36674856, 2023). "MDM2 amplification is one of the key diagnostic markers for liposarcoma, and it is often used to differentiate it from other types of sarcomas." (PMID 37297833, 2023). "Overall, these suggest that the MDM2 gene can not only become amplified, which is a hallmark of well-differentiated liposarcoma/atypical lipomatous tumor, but also can be targeted treatment outcomes for sarcoma and other cancers." (PMID 37297833, 2023). "Dedifferentiated liposarcomas showed MDM2/CDK4 gene amplifications, as already detected by diagnostic cytogenetics (TOMAS-43, TOMAS-48; both responder patients)." (PMID 36110934, 2022). "MDM2 amplification is a diagnostic criterion for liposarcoma in soft tissue, but at least 80% liposarcomatous differentiation in malignant PT and MC are unassociated with MDM2/CDK4 amplification." (PMID 35814458, 2022). "High-level amplification of MDM2 and other genes in the 12q13–15 locus is a hallmark genetic feature of well-differentiated and dedifferentiated liposarcomas (WDLPS and DDLPS, respectively)." (PMID 34986184, 2022). "ISAs of uncommon sites such as the retroperitoneum, where dedifferentiated liposarcoma is always a strong consideration, are prone to be misdiagnosed, especially in conjunction with an underlying MDM2 amplification." (PMID 34312479, 2021). "The sarcomas in which MDM2 amplification is a hallmark are well-differentiated liposarcoma/atypical lipomatous tumor, dedifferentiated liposarcoma, intimal sarcoma, and low-grade osteosarcoma." (PMID 33799733, 2021).
liposarcoma (continued). "Many genetic mutations have been reported in dedifferentiated liposarcomas, including mutations in MDM2, CDK4, high mobility group AT-hook 2 (HMGA2), fibroblast growth factor receptor substrate 2 (FRS2), and neuron navigator 3 (NAV3), all located in 12q13-15." (PMID 35008848, 2021). "MDM2 is responsible for the development of dedifferentiated liposarcomas that cause antiapoptotic effects and the dedifferentiation of tumors." (PMID 35008848, 2021). "Our previous work demonstrated that higher levels of MDM2 amplification are associated with worsened overall survival and resistance to DNA-damaging chemotherapy in liposarcomas." (PMID 32759684, 2020). "The immunohistochemical trio of CDK4, MDM2, and p16 is a useful ancillary diagnostic tool that provides strong support for distinguishing differentiated liposarcoma from other adipocytic neoplasms." (PMID 32997268, 2020). "Strong staining for MDM2 or CDK4 associates with 12q14‐15 amplification in liposarcoma or well‐differentiated osteosarcoma." (PMID 30667539, 2019). "Although PDLIM7 is ubiquitously expressed in the liposarcoma and non-small cell lung cancer cell lines we examined here, its association with MDM2 was cell type and condition specific." (PMID 29789718, 2018). "In well-differentiated and dedifferentiated liposarcoma their clinical promise is associated with their ability to downregulate the MDM2 protein." (PMID 29789718, 2018). "In conclusion, this work is the first to report the entire genome of a well-differentiated liposarcoma with novel chromosomal rearrangements associated with amplification of therapeutically targetable genes such as MDM2 and DDR2." (PMID 24505276, 2014). "High MDM2 expression is often observed in liposarcomas and is currently used as a cancer diagnostic biomarker." (PMID 24147044, 2013). "MDM2 gene amplification serves as the strongest predictive biomarker, defining a patient population with demonstrated susceptibility to MDM2 inhibition, particularly in sarcomas such as dedifferentiated liposarcoma, where near-universal amplification occurs." (PMID 41170373, 2025). "Amplification of MDM2, a crucial molecular marker, is key to distinguishing benign lipomas and their variants from locally aggressive counterparts such as atypical lipomatous tumors and well-differentiated liposarcomas." (PMID 40515886, 2025). "Kindled by the compelling importance of MDM2 assessments to improve diagnostic and therapeutic liposarcoma management, these suggestions could represent the first step to develop a univocal interpretation model and consensus guidelines." (PMID 36674856, 2023). "The objective of this study was to evaluate and validate the predictive performance of multimodality imaging-derived models using computer-aided diagnostic (CAD) methods for prediction of MDM2 gene amplification to identify well-differentiated liposarcoma (WDLPS) and lipoma." (PMID 35392952, 2022). "Thus, MDM2 amplification is an essential diagnostic tool to diagnose liposarcomas and in practice it can be found with FISH." (PMID 35626152, 2022). "In addition, well-differentiated liposarcoma and dedifferentiated liposarcoma are associated with amplifications in a specific region on chromosome 12 (12q13-15) that encompasses genes such as MDM2 and CDK4." (PMID 34440251, 2021). "However, it was reported that increased MDM2 amplification was closely associated with histological grade in liposarcomas." (PMID 31160689, 2019). "MDM2 amplification was most commonly associated with liposarcoma." (PMID 30237864, 2018).